PARP1 (poly(ADP-ribose) polymerase 1)
Diseases named in the same sentence as PARP1 in open-access papers (continued):
Sharing a sentence is not in itself a finding about the gene and the disease.
tumor (continued). "S‐sulfhydration of MEK1 by H2S at Cys341 promotes phosphorylation and nuclear translocation of MEK1, thereby activating PARP‐1‐mediated DNA damage repair, which is most likely a key driver of tumour growth due to CBS or CSE overexpression." (PMID 36929586, 2023). "Such a finding is of significant interest considering the remarkable success of PARP1 inhibitors in the clinic and presents a potential new drug target for tumours expressing mutant KRAS, which has hitherto proven difficult to target directly." (PMID 36648336, 2023). "Simultaneously, we also found that HIF-1a was expressed at higher levels in SKA3-overexpressing tumours of nude mice than in NC tumours, while PARP1 knockdown reversed this effect." (PMID 37821935, 2023). "A high overall expression rate was seen for PARP-1 (97%), with positive staining of tumor nuclei, albeit heterogeneously." (PMID 36835265, 2023). "In the case of DCs, the NPA gene, CHMP1B was up-regulated in tumor tissues, while PARP1 was down-regulated in tumor samples." (PMID 38149248, 2023). "We reviewed the current research on the role of PARP1 inhibitors in tumor radiotherapy sensitization." (PMID 38111536, 2023). "From the in vivo studies using EAC-mice, the CDA-dextran conjugates displayed a higher anticancer activity as revealed from the EAC tumor size, weight, and biochemical markers Caspase-independent apoptotic markers PARP-1 and AIF." (PMID 36627557, 2023). "The function of PARP-1 in a tumoral context is complex since there is a crosstalk between it and the dynamic of tumour microenvironment." (PMID 36902215, 2023). "The correlation between PARP trapping and tumor sensitivity provided a strong argument for the PARP-1 trapping model." (PMID 37609662, 2023). "The investigational PARP-1 and PARP-2 inhibitor Pamiparib has also shown promising antitumor efficacy, suppressing the proliferation of tumor cell lines harboring BRCA1/2 mutations or HRD." (PMID 37351512, 2023). "According to some of the earlier works, despite showing potent in vitro cytotoxic activity, PARP-1 inhibitor monotherapy showed limited clinical activity in certain tumor types." (PMID 36834491, 2023). "Inhibition and inactivation of PARP1 induces growth arrest/apoptosis signaling and tumor suppression." (PMID 37808268, 2023). "Following 48 h of treatment, a dose-dependent cleavage of PARP-1 (89 kDa fragment) was observed in PC-3 tumor cells." (PMID 38248645, 2023). "PARP1 has emerged as a target with great therapeutic potential for some tumor types, drawing attention to this enzyme and resulting in many small molecule inhibitors of its enzymatic activity." (PMID 37240195, 2023). "Overall, our results underline the link between MARVELD1 and PARP1 in therapeutic resistance based on DDR and provide new insights for clinical tumor therapy of PARPi." (PMID 36750717, 2023). "Particularly, coinhibition of MALAT1 and PARP1 exhibits a decline in clonogenic survival, delays resolution of γH2AX foci, and reduces tumor burden in mice xenograft model." (PMID 37812088, 2023). "PARP-1 inhibitors can be used in combination with ionizing radiation or chemotherapy to enhance the sensitivity of tumor cells to these treatments." (PMID 37351512, 2023). "Subsequently, to examine the coinhibitory potential of MALAT1 and PARP1 in distant tumor metastasis, we determined the levels of human-specific Alu sequences in the lungs and bone marrow collected from xenografted mice." (PMID 37812088, 2023). "PARP1 inhibitors kill tumor cells after chemotherapy drugs have damaged the cell’s DNA by interfering with DNA damage repair." (PMID 38111536, 2023). "Chromosomal rearrangements resulting from PARP1 abrogation lead to a second hit in the PTCH1 allele, increasing the incidence of tumor formation." (PMID 35747808, 2022).
tumor (continued). "The four genes have been found to influence tumor progression in HNSCC via necroptosis regulation; Poly (ADP-ribose) polymerase-1 (PARP1), as a chromatin-associated enzyme in DNA repair; and a downstream effector of RIPK1/RIPK3 pathway in necroptosis." (PMID 36349193, 2022). "Synergistic use of more innovative therapies such as the poly (ADP-ribose) polymerase-1 (PARP-1) inhibitor Olaparib has been shown to increase sensitivity of tumor cells to PRRT in vitro." (PMID 35159027, 2022). "In one recent study, PARP1 expression was observed in 100% of DSRCT tumor samples (N = 16) and its inhibitor, olaparib, reduced DSRCT cell viability and migration." (PMID 35379887, 2022). "Mouse xenograft studies have shown that the DNA-PK inhibitor AZD7648 can enhance the efficacy of olaparib, a PARP1/2 inhibitor, in FaDu ATM knockout (KO) tumour models, since the loss of ATM has been shown to sensitise cells to DNA-PK inhibitor treatment." (PMID 35617197, 2022). "These early clinical studies indicate safety and feasibility of visualizing tumors/quantifying PARP1 expression in a range of tumor types." (PMID 35267438, 2022). "Recent studies have shown that PARP1 makes an essential contribution to NK cell biology, for instance, in gathering NK cells to a virus-infected area and participating in killing tumor cells." (PMID 36091054, 2022). "[18F]FTT displayed a good affinity (IC50 = 6.3 nM) towards PARP1 and showed specific tumor uptake (3–5% ID/g 1 h p.i.)in MDA-MB-231 and MDA-MB-436 xenograft models." (PMID 35267438, 2022). "The results revealed that RGD-Exo-circDIDO1 treatment led to an obvious increase of cleaved caspase 3 and cleaved PARP1 protein levels in tumor tissues." (PMID 35864511, 2022). "Using the median tumor regression rate of 34%, we divided the entire cohort into two groups, and found that the frequency distribution of PARP-1 gene rs3219073 had significant difference between these two groups (p < 0.05)." (PMID 36590386, 2022). "SNORD104 is upregulated in EC and promotes tumor growth by inducing 2ʹ-O-methylation of PARP1, which enhances the latter’s expression and biological function." (PMID 36566215, 2022). "Pharmacologically, tumour cells are in general more sensitive to PARP1 inhibition than healthy cells." (PMID 36078035, 2022). "From the results of the tumor-associated genes analysis, the most significant ten tumor- associated genes such as SNAI2, VCAM, MMP2, BRCA1, PARP1 and MECOM were closely associated with UCPs." (PMID 35090503, 2022). "PARP-1 inhibitors with distinct scaffolds exhibit vastly different anti-tumor efficacy in the clinic." (PMID 36353483, 2022). "In the authors’ opinion, the main interest should be focused on the type of tumor with alterations to the HR genes since the studies showed that cells of this type are ‘hyper-dependent’ on Polθ mediated repair (like with PARP1)." (PMID 35741863, 2022). "As PARP-1 has broad synergistic effect with other targets in anti-tumor studies, these compounds also provide the alternative active scaffold for the further multi-targeting drug design by combining PARP-1 with LdTop1 or α-glucosidase." (PMID 36353483, 2022). "PARP1 expression in PSN1 tumours was heterogeneous, hence resulting in heterogeneous uptake of [18F]rucaparib." (PMID 35614267, 2022). "With DNA damage induced by alkylating agents in tumor cells, PARP1 reduces the affinity of EZH2 for H3K27 sites and inhibits its enzymatic activity through PARylation, while poly ADP-ribose glycohydrolase (PARG) can reverse this effect." (PMID 36263120, 2022). "For tumor cells with BRCA1/2- or HR- deficiency, PARP1 activity is important for preventing the spontaneous ssDNA breaks that results in accumulation of DSBs." (PMID 36284291, 2022). "Although not as potent as olaparib, the NAD derivative MNA was effective at inducing ROS and induced the anti-tumor activity of macrophages, including in PARP1-null macrophages." (PMID 36223740, 2022).
tumor (continued). "The role of PARP-1 expression in tumor grade is ambiguous; high tumor grade has been reported to correlate with low (p = 0.003) or high PARP-1 expression in BC." (PMID 35406503, 2022). "The PARPi-FL in the tumor was able to localize to accordant targets in cell nuclei, where they bind to PARP1 and are released to play the key role of an imaging agent." (PMID 36015275, 2022). "Here, the authors sequence primary and recurrent tumours of BRCA1/2 mutation carriers, finding PARP1 amplifications, differential BRCA2 isoform usage, and discordant loss of heterozygosity that are associated with recurrence." (PMID 36344544, 2022). "DOX-loaded P/LNVs directly increased the expression and presentation of endogenous tumor antigens in situ by inducing immunogenic cell death in B16 cells via the poly (ADP-ribose) polymerase 1-dependent (PARP1) apoptotic pathway." (PMID 35223804, 2022). "PARPs are readily druggable and PARP inhibitors (PARPi) against the main DDR-associated PARPs, PARP1 and PARP2, are currently approved for the treatment of a range of tumor types." (PMID 36533080, 2022). "Surprisingly, macrophages were redirected toward a pro-inflammatory, anti-tumor phenotype if we inhibit the PARP enzymatic activity in WT (PARP1 and PARP2 intact), PARP1-null (PARP2 intact), or PARP2-null (PARP1 intact) cells." (PMID 36223740, 2022). "The expression of XRCC2 and PARP1 in biopsy tumor specimens collected from 167 LARC patients before treatment with neoCRT followed by surgery indicated that 57 samples (34.1%) were XRCC2+ and 52 samples (31.1%) were PARP1+." (PMID 35643812, 2022). "In this study, we analyzed the expression levels of PARP1 protein in tumor cells (CK+) and stroma cells (CK-) from EOC tissues using multiplex immunofluorescence assay." (PMID 35875162, 2022). "A quantitative evaluation of the relative sensitivities of detection of PARP-1 expression changes across tumor cell lines by [18F]-PARPZ in vivo correlated by other molecular biotechniques is warranted to fully evaluate this promising new tool." (PMID 35906379, 2022). "Some past research has shown that the tumor microenvironment is made up of more than just tumor cells and also involves stromal cells and infiltrating cells of the immune system, which are likely affected by PARP1 inhibition." (PMID 35875162, 2022). "Both EZH2 and PARP1 are multitargets, so targeting tumor cells through novel drug loading and delivery systems is one of the solutions to improve the existing therapeutic efficacy in this case." (PMID 36263120, 2022). "The higher PARP1 expression of tumor cell nuclei is a possible explanation for the selective toxicity in tumor cells, but further mechanistic studies are necessary to confirm this or investigate other explanations." (PMID 35267438, 2022). "We surmise that the increase in this metric is a function of both therapy induced DNA damage induced expression of PARP-1, as well as increased tumor cell PARP-1 expression in controls resulting from tumor progression." (PMID 35906379, 2022). "In the present study, PARP-1 was also found to be highly expressed in tumor cells from AML patients and in K562 cells." (PMID 35130631, 2022). "On the other hand, the occurrence of parthanatos mainly comes from the abnormal activation of PARP-1, so it can also lead to the occurrence of parthanatos in tumor cells by enhancing the activity of PARP-1 to inhibit the proliferation of tumor cells." (PMID 35963853, 2022). "The superimposed deduction of BRCA1, RAD51 and PARP1 with both sc-13 and NU-7441 treatment indicated the two essential pathways critical for tumor cell replication and genome stability in response to replication stress." (PMID 35414100, 2022). "Most tumours overexpress PARP1 in response to increased DNA damage aggravated by radiation and chemotherapy treatment." (PMID 36078035, 2022).
tumor (continued). "This suggests that 8-oxoG repair enzymes contribute to the function of PARP1 inhibitors for tumor therapy." (PMID 36497058, 2022). "PARP1 and PARP2 transcript levels were significantly higher in tumor than all peri-tumor and control tissues except NASH-associated tumors." (PMID 35804391, 2022). "Mir-21 has been inversely related to apoptotic processes, so we studied the expression of the PARP-1 protein, and this was directly related to tumor vascular increase, so we also studied the VEGF protein." (PMID 36499129, 2022). "Most notably, the two lowest PARP1-expressing tumor types (COG-N-519x and COG-N-426x-felix) demonstrated robust responses in vivo." (PMID 36396952, 2022). "The uptake correlated with PARP1 expression and was validated to be tumor specific in blocking experiments, autoradiography, and by using a fluorescent analogue (PARPi-FL) for microscopic evaluation." (PMID 35267438, 2022). "In this study, we tried to discover novel anti-tumor compounds targeting PARP-1 by computer simulations and in vitro screening." (PMID 36353483, 2022). "In this study, we discovered a novel mechanism of HR suppression regulated by miRNA-363-3p, and PARP1 inhibition significantly increased the anti-tumor activity of chemotherapeutic drugs in this context." (PMID 35488020, 2022). "In-vitro studies showed a good tumor uptake of 18F -olaparib in PARP-1-expressing Capan-1 and MiaPaCa cells." (PMID 35295604, 2022). "The BBB has always represented a major obstacle to the delivery of drugs to GBM tumours, and PARP-1 inhibitors have shown some success in clinical studies in overcoming this." (PMID 35158955, 2022). "We further divided the entire patient cohort into two groups using the median tumor regression rate of 34.0%, and found that the frequency distribution of PARP-1 gene rs3219073 between the two groups had significant difference (p < 0.05)." (PMID 36590386, 2022). "Previously, the induced autophagy by PARP-1 inhibitors was reported in other tumor cells, but not in HCT-116." (PMID 36353483, 2022). "Seventy percent of all patients (19/27) in the cohort had a PARP1 gain or amplification in at least one tumor (85% of breast patients, 57% of ovarian patients)." (PMID 36344544, 2022). "In HCC, NF90 was also shown to regulate the stability of Poly(ADP-Ribose) Polymerase 1 (PARP1) mRNA, and therefore promote tumor development." (PMID 36362366, 2022). "The aim of the study was to determine PARP-1 expression and BRCA1 mutations in circulating tumor cells (CTCs) of BC patients." (PMID 35406503, 2022). "SNORD104 enhances PARP1 mRNA stability and translation in the EC cells by upregulating 2ʹ-O-methylation and promotes tumor growth." (PMID 36566215, 2022). "Our previous PDX studies revealed that the inhibition of PARP1, the subsequent suppression of CEGRs/ALCDs, and tumor growth were mediated by the reduced expression of CEGRs/ALCDs-dependent genes." (PMID 36551548, 2022). "PARP-1 has a key role in chronic inflammation in the context of many inflammatory-driven pathologies as well as in tumours." (PMID 35158955, 2022). "RAD52-mediated DNA repair remains active in PARPi-treated BRCA-deficient tumor cells such that dual inhibition of RAD52 and PARP1 have demonstrated evidence of synthetic lethality in a BRCA-deficient mouse model." (PMID 35626165, 2022). "The authors observed that [18F]FTT tumor uptake was decreased in olaparib treated animals compared to untreated animals, concluding that the tracer is suitable to measure PARP1 expression in vivo." (PMID 35267438, 2022). "In fact, most of the neighbor genes’ expression of PARP1 (64/72) are significantly different in tumor and normal tissues per Wilcoxon rank sum test with continuity correction (P-value < 0.05)." (PMID 36266635, 2022). "PARP1 staining of tumour, liver and thyroid proved the nuclear localisation of PARP1 only in tumour and not in liver and thyroid." (PMID 36104637, 2022).
tumor (continued). "In colorectal cancer level of PARP1 expression was positively correlated with tumor size and histopathological features according to TNM classification system." (PMID 36533080, 2022). "To further investigate the correlation between injected mass, [18F]olaparib tumour uptake and target expression, we employed immunohistochemistry to semi-quantitatively compare PARP1, 2, and 3 expression in U87MG xenografts." (PMID 36210377, 2022). "PARP-1 inhibition is currently under investigation to evaluate its efficacy to sensitize GBM tumours to chemotherapy and radiotherapy." (PMID 35158955, 2022). "It was shown that preincubation of tumor cells with Fluzaparib (inhibitor of PARP1) reduced the cytotoxic activity of the derivatives 3 and 4 by more than twice." (PMID 36234755, 2022). "The impact of PARP1 expression in epithelial tumor cells and stroma cells on platinum resistance and prognosis was investigated using microarray analysis." (PMID 35875162, 2022). "One of the most important functions of PARP-1 is to participate in DNA repair, which is conducive to the survival of tumor cells." (PMID 35963853, 2022). "[125I]KX1 showed high tumor uptake but low specific binding to PARP1 based on a blocking study using Olaparib and severe deiodination was also observed." (PMID 36438061, 2022). "Taken together, these results demonstrated that inhibition of AKT enhanced the response of tumor cells to PARP inhibitor in ovarian cancer cell lines with high PARP1 protein expression level, corroborating the effect observed in PDX model study." (PMID 35419627, 2022). "Inhibition of PARP1 by olaparib has been tested in clinical trials for tumours of different origins." (PMID 36078035, 2022). "SCLC over-expresses PARP-1, whose inhibition was found to up-regulate intra-tumor T cell infiltration and to synergize with PD-L1 blockade, provoking substantial tumor decrease in mouse models." (PMID 36428727, 2022). "PARP transcripts (qPCR) and PARP1, H2AX and gammaH2AX protein (RPPA) levels were compared in control liver vs HBV-, HCV-, alcohol- and NASH-associated HCC (Tumor/Peri-Tumor) tissues." (PMID 35804458, 2022). "The double deficiency of PARP-1/PARP-2 reduces the number of infiltrating T and NK cells in the microenvironment, creating an environment conducive to tumor growth." (PMID 35906622, 2022). "Our work supports the idea that reduction of pADPr level and PARP-1 activity is also critical for anti-tumor effects as the PARG overexpression approach demonstrated similar phenotype." (PMID 34638458, 2021). "This was confirmed by genetic manipulation of PARP1 expression in OXA-resistant organoids used in subcutaneous tumor formation." (PMID 34497808, 2021). "At the same time, the overexpression of PARP1 can afford the possibility to defeat tumor with greater specificity." (PMID 33809749, 2021). "PARP1 IHC also showed significantly higher expression in tumor regions in both HPV-positive and HPV-negative oropharyngeal samples." (PMID 34194286, 2021). "In conclusion, our results suggest that PLA2R1 suppresses aging-induced tumors by repressing PARP1, via a ROS–Rb signaling axis, and inducing DNA damage and its tumor suppressive responses." (PMID 33594040, 2021). "The high level of endogenous pADPr appears to be the best predictor of tumor responsiveness to PARP-1 inhibition." (PMID 34638458, 2021). "Accordingly, PARP1 expression at the protein and RNA level correlated positively with increasing tumor grade and poorer overall survival compared to reference samples." (PMID 34439854, 2021). "It has been reported 289 that PARP1 suppresses tumor initiation after DNA alkylation but also promotes tumor progression driven by inflammation." (PMID 33384409, 2021). "PARP-1 is able to promote (directly or indirectly) epigenetic modifications, creating conditions for development of heterogeneity of tumor cells and formation of super-resistant clones in a heterogeneous population." (PMID 34768872, 2021).